LEPR (leptin receptor)
Diseases named in the same sentence as LEPR in open-access papers (continued):
Sharing a sentence is not in itself a finding about the gene and the disease.
diabetes (continued). "Once released, leptin affects cells by binding to the leptin receptor OB-R, the product of the diabetes (db) gene." (PMID 26593914, 2015). "In an attempt to study DNA copy number variations associated with metabolic traits and type 2 diabetes mellitus (T2DM), we targeted the LEPR gene locus in DNA copy number analyses." (PMID 20624279, 2010). "In the hyperglycaemic LepR−/− animals, sclerostin levels were substantially higher than in the euglycaemic LepR+/+ animals at both time points, which is in accordance with clinical findings in type 2 diabetes mellitus patients." (PMID 37730735, 2023). "Db/db mice, or leptin-receptor-deficient mice, are homozygous for an autosomal recessive point mutation of a diabetes gene (db), resulting in an absence of the long isoform of the leptin receptor." (PMID 37509384, 2023). "While the effect of LEPR rs4655555 on the development of BC has not yet been reported, one study has shown that rs4655555 is significantly correlated with plasma soluble leptin receptor levels and may inform diabetes prognosis." (PMID 36253742, 2022). "In this regard, selective expression of leptin receptors in hypothalamic POMC neurons has been shown to prevent diabetes in leptin receptor-deficient db/db mice, independent of changes in food intake and body weight." (PMID 35527735, 2022). "Mice with mutations in the leptin receptor gene (db/db) show an almost indistinguishable phenotype to that of ob/ob mice, except that the db/db mice exhibit an increased degree of diabetes and some variation of fat distributions." (PMID 35454105, 2022). "Similarly, the KEGG pathways antigen processing and presentation pathway, complement and coagulation cascade pathway and type 1 diabetes mellitus pathway were obviously enriched in TAO patients with LEPR gene up‐regulation." (PMID 33988300, 2021). "Additionally, clusterin alleviates endothelial dysfunction in Leptin receptor-deficient diabetic (db/db) and Streptozotocin (STZ)-induced diabetes by activating AMPK46." (PMID 33060605, 2020). "There is an important potential source of type II error β in the inference that LEPR genetic variants does not contribute to diabetes-susceptibility in our meta-analysis." (PMID 29293570, 2018). "Typically, hyperglycemia is less severe in ob/ob mice and in leptin receptor-deficient mice on the C57BL/6J background, whereas db/db mice on the C57BLKS background develop fulminant diabetes and require exogenous insulin administration in order to maintain well-being beyond 24 weeks of age." (PMID 26814757, 2016). "ZDF (fa/fa) develop diabetes due to being homozygous for a spontaneous mutation that leads to a non-functional leptin receptor as well as a second mutation that impairs β-cell function." (PMID 24086387, 2013). "Finally, to test the role of the leptin receptor in aberrant macrophage polarisation, we obtained Lepr−/− macrophages from 3-week-old pups, prior to the onset of diabetes." (PMID 24057002, 2013). "For example, in diabetic patients, leptin receptor mutations are quite infrequent, and therefore genotypic animal models may not resemble the real pathophysiology of diabetes." (PMID 38745946, 2024). "This rat does not carry the leptin receptor mutation (fa/fa) and develops a prediabetic state that progresses to overt diabetes with age, with common morbidities, such as cardiomyopathy, that are associated with an increased risk occurrence in prediabetic patients." (PMID 36674935, 2023). "The monogenic mutation of the Leptin receptor might not represent the clinical development of diabetes, however, the model provided important information about diminished leptin signaling in IVDs." (PMID 32374776, 2020). "In addition, genes linked to human T2DM form genome wide association studies (GWAS) of human diabetes do not include genes of leptin and leptin receptor (Wang, Chandrasekera & Pippin, 2014)." (PMID 29682407, 2018).
diabetes (continued). "Here, we established two murine diabetes models: STZ-induced type 1 diabetes and leptin receptor knockout (db/db)-induced type 2 diabetes, along with a H-glu-stressed HCEC model." (PMID 41146365, 2025). "Therefore, if FTO can regulate LEP and LEPR expression, this could also lead to an altered expression of IL-6 and TNF-α and a significant susceptibility to the development of chronic diseases such as type 2 diabetes mellitus." (PMID 38474283, 2024). "Leptin and soluble leptin receptor levels are increased in T1DM children and related to anthropometrics parameters, metabolic control, age of debut of diabetes, and kind of insulin therapy." (PMID 36674935, 2023). "We have opted for repeated injections of small doses of STZ over high-fat diet or leptin receptor deficiency animal models of diabetes to enable cell lineage tracing and rule out any indirect effects, mediated by changes in insulin sensitivity or blood glucose, that may impact the islet plasticity." (PMID 34191257, 2022). "A potential confound of using db/db mice is that AIS shortening could be a byproduct of the db/db genetic model, and not the development of diabetes, as they are leptin receptor-deficient and leptin signaling is involved in the neuronal and glial development of mouse embryos." (PMID 29937715, 2018). "In this study, db/db mice lacking leptin receptor were used to evaluate the effects of crocodile blood on endothelial functions in type 2 diabetes mellitus." (PMID 40477401, 2021). "One study observed that LEPR wt/- mice, unlike LEPR -/- mice, did not develop diabetes due to a compensatory mechanism leading to suppression of beta-cell apoptosis." (PMID 34448070, 2021). "LepR-KO mice developed impaired glucose tolerance and insulin resistance in the absence of frank diabetes, with restoration of blood glucose through increased beta cell function and mass." (PMID 27003683, 2016). "LepR-KO mice do not develop frank diabetes by compensating, in part, through increased beta cell function." (PMID 27003683, 2016). "LepR deficiency induced a doubling of body mass within 3 weeks, with moderate glucose intolerance (unlike typical LepR mutant mice [db/db], which have frank diabetes)." (PMID 27003683, 2016). "A significant advantage to using the KK-Ay strain is that diabetes is polygenic and not due to a defect in leptin receptor signaling." (PMID 23710468, 2013). "Transporter mRNA and protein expression were quantified in livers and kidneys of adult C57BKS and db/db mice, which have a severe diabetes phenotype due to a lack of a functional leptin receptor." (PMID 22524730, 2012). "db/db mouse is a model of diabetes because it has no leptin receptor activity." (PMID 24688594, 2014). "Moreover, the obtained results also indicated a statistically significant difference in the concentration of the soluble leptin receptor between the group of sick individuals with diabetes, who were not subject to the therapy, and the subjects from the control group." (PMID 28758947, 2017).
type 2 diabetes (187 papers, 2008 to 2026). "SDT-f rat is a type 2 diabetes model in which a leptin receptor mutation is introduced into the genetic background of SDT rats." (PMID 40402578, 2025). "Leptin receptor-deficient Db/db mice (n = 7, 24-week-old, male) were employed as a type 2 diabetes model, while age-matched male C57BL/6J mice (n = 7) served as normal controls." (PMID 40636148, 2025). "Polymorphisms in the LEPR gene are associated with type 2 diabetes and related metabolic traits in a Chinese population." (PMID 39845086, 2024). "Based on a meta-analysis of 16 studies involving 7827 participants, evidence shows that the Gln223Arg polymorphism in LEPR is unrelated to vulnerability to type 2 diabetes." (PMID 38198642, 2023). "Researchers recognized two polymorphisms: Lys109Arg, and Gln223Arg; there is a strong correlation between extracellular regions of the leptin receptor and conversion to type 2 diabetes in IGT patients with a higher risk." (PMID 38198642, 2023). "In the present study, we used leptin-receptor-deficient db/db mice, a mouse model of type 2 diabetes, to investigate the effect of EchA on DN progression and gain more insight into the mechanisms underlying the beneficial action of EchA in vivo." (PMID 37103361, 2023). "A meta-analysis revealed a connection between LEPR gene polymorphism (rs1137101) and type 2 diabetes risk." (PMID 38198642, 2023). "While numerous genes have been allied to an increased predisposition for emerging Type 2 Diabetes, the LEPR gene stands out as particularly significant, especially in specific populations." (PMID 38198642, 2023). "Numerous research teams conducted genetic association studies on many ethnic communities to study the connection between genetic variants in the LEPR gene and type 2 diabetes susceptibility." (PMID 38198642, 2023). "For proof-of-concept purposes, this platform was applied to a mouse model of type 2 diabetes (T2DM) using mice with a spontaneous mutation of the leptin receptor (db/db)." (PMID 35881173, 2022). "Another disadvantage of monogenic animals is the high mortality of certain strains due to ketosis, e.g., db/db mice have a mutation of the leptin receptor and yet are widely used as a model of diabetes type 2." (PMID 35782067, 2022). "For type 2 diabetes, the genetically predisposed leptin-deficient ob/ob or leptin receptor-deficient db/db mice recapitulate well the human metabolic syndrome." (PMID 35883655, 2022). "According to previous studies, several polymorphisms of the LEPR gene, such as Arg109Lys (rs1137100), Gln223Arg (rs1137101) and Asn656Lys (rs8179183), were reported to be associated with type 2 diabetes." (PMID 36077028, 2022). "Genetic polymorphisms in the genes coding for leptin (LEP) and the leptin receptor (LEPR), particularly SNPs, have been demonstrated to be associated with adult obesity, childhood obesity or type-2 diabetes." (PMID 36289764, 2022). "We have demonstrated its utility for measuring endogenous concentrations within a mouse model of type 2 diabetes (T2DM) using mice with a spontaneous mutation of the leptin receptor (db/db)." (PMID 35881173, 2022). "The specific mouse model was selected as the leptin receptor gene mutation in BKS-Leprdb mice increases susceptibility to type 2 diabetes." (PMID 35725532, 2022). "The db/db mouse is an accepted genetic model of type 2 diabetes due to a mutation in the leptin receptor." (PMID 34031437, 2021). "An established system for studying type II diabetes is the leptin receptor deficient db/db mouse model." (PMID 34357335, 2021). "In this study, we used 8-week-old female leptin-receptor deficient db/db mice, characterized by hyperglycemia and impaired wound healing, as a model for type II diabetes mellitus." (PMID 34200896, 2021).
type 2 diabetes (continued). "It was proposed that GCN2 was involved in programming the “thrifty phenotype” and that GCN2-deficient leptin receptor-mutated mice displayed a reduced capacity to store triglycerides and an increased susceptibility to developing type 2 diabetes." (PMID 33299856, 2020). "In our study, db/db mice, leptin receptor-deficient mice, were chosen as the type 2 diabetes animal model." (PMID 32257541, 2020). "In our in vivo experiments, we selected an animal model of type 2 diabetes, db/db mice, a spontaneous type 2 diabetic mouse caused by a defect in the Leptin receptor gene on chromosome 4 discovered by the Jackson Laboratory in the United States in 1966." (PMID 32636757, 2020). "The C57BLKS-Leprdb mouse (db/db mouse) is homozygous for a mutation in its leptin receptor (Lepr) gene and is a well-established animal model for type 2 diabetes and MetS." (PMID 33148888, 2020). "The db/db mouse, a spontaneous model of type 2 diabetes, carries a G-to-T point mutation of the leptin receptor on chromosome 4 that leads to hyperphagia, decreased energy expenditure, hyperglycemia, and insulin resistance." (PMID 31687039, 2019). "An in vivo type 2 diabetes treatment study showed the enhancement of serum GLP-1 from oral administration of a hIgG1-Fc-9Arg/pGLP-1 complex to the leptin-receptor deficient mouse (Lepdb/db)." (PMID 30065848, 2018). "The leptin receptor-deficient db/db mice, a severe obese and type 2 diabetic mouse model, exhibit defective VSMC coverage and a large increase in the amount of smaller-diameter nerve bundles with myelin sheath and unmyelinated nerve fibers." (PMID 29323138, 2018). "Taking this into account, we conducted this study to investigate the association of the selected polymorphisms of LEPR with type 2 diabetes in a Chinese population." (PMID 29301582, 2018). "Various genetic association studies were performed to evaluate associations of LEPR genetic variants with type 2 diabetes (T2D) susceptibility." (PMID 29293570, 2018). "We herein investigated the skeletal effects and mechanisms of PEMF (15 Hz, 20 Gs) on leptin receptor-deficient db/db mice with typical type 2 diabetic symptoms." (PMID 28883516, 2017). "To independently confirm these results, we used db/db mice that carry a mutation in the leptin receptor gene and are a well-established model of type 2 diabetes and are characterized by liver steatosis." (PMID 28608850, 2017). "Commonly used models of DN include Streptozotocin (STZ), a model of type I diabetes, and models of type 2 diabetes that use animals with leptin deficiency (ob/ob mice) or leptin receptor deficiency (db/db mice, Zucker Diabetic Fatty rats)." (PMID 28746409, 2017). "In the current study, we investigated the mechanism underlying lysosomal dysfunction in the cortex and hippocampi, key structures involved in learning and memory, of a type 2 diabetes (T2D) mouse model, the leptin receptor deficient db/db mouse." (PMID 25976368, 2016). "The leptin receptor-deficient db/db mouse is a well-established type II diabetes animal model used to investigate diabetic cardiomyopathy." (PMID 25292177, 2014). "Similar mutations in leptin and the leptin receptor also occur in humans and have been linked to type II diabetes." (PMID 24618995, 2014). "In order to confirm our findings in an additional model of type II diabetes we repeated the same set of experiments in a second well characterized model in which mice carry a leptin receptor null mutation: the C57BLKS db/db (db/db) mouse line." (PMID 24961298, 2014). "Among various predisposing genetic loci, a pentanucleotide (CTTTA) Del/Ins variant in the 3'-UTR of the LEPR gene is associated with type 2 diabetes and its related traits." (PMID 25580385, 2014). "The leptin receptor-deficient db/db mouse is a well established model of type II diabetes, with obesity and insulin resistance." (PMID 25292177, 2014).
type 2 diabetes (continued). "DDAH-1 expression was reduced during diabetogenesis in the liver, kidney and adipose tissue of mice with a point mutation in leptin receptor, an experimental motel of type 2 diabetes." (PMID 23578341, 2013). "The purpose of this review is to introduce two new polygenic mouse models of type 2 diabetes (T2D) and to contrast them with the most commonly studied monogenic model, the leptin receptor-deficient C57BLKS/J-Leprdb/Leprdb(hereafter abbreviated as db/db) mouse." (PMID 23671854, 2013). "In this study, we used leptin receptor deficient type 2 diabetes model mice (db/db) and prediabetic C57BL/6J mice." (PMID 23675258, 2012). "At first, we administered algae homogenate to leptin receptor deficient db/db mice, well known models of type 2 diabetes." (PMID 23675258, 2012). "It is unlikely that the findings of the present study are a direct result of leptin receptor deficiency since abnormal vascular responses to serotonin are observed in other leptin-independent murine models of type 1 and type 2 diabetes." (PMID 23346101, 2012). "We administered these algae homogenate to leptin receptor deficient db/db mice that are known as model mice of diabetes type 2 and evaluated them in terms of the down-regulating ability of blood glucose." (PMID 23675258, 2012). "In the db/db mouse type 2 diabetes is linked to a dysfunctional leptin receptor, and the mouse is hyperphagic, massively obese with marked hyperglycemia and has been widely used for the study of type 2 diabetes." (PMID 21785580, 2011). "The leptin receptor deficient db/db mouse is a widely utilized mouse model of type 2 diabetes as it displays several of the features of human type 2 diabetes at 12 weeks of age." (PMID 22087215, 2011). "The data presented in the current study is in accordance with data from the leptin-receptor-deficient (db/db) mice which also exhibits the typical features of type 2 diabetes with hyperglycemia, dyslipidemia, and hyperinsulinemia." (PMID 21785580, 2011). "In our previous study in a leptin receptor deficient model of Type 2 diabetes, contractions of arteries from diabetic female mice were increased to serotonin similar to increases in arteries from diabetic male mice." (PMID 20368772, 2010). "Based on the meta-analysis findings, genetic variants of the LEPR gene may make people more prone to acquiring type 2 diabetes." (PMID 38198642, 2023). "This study sought to establish whether polymorphisms in the LEPR gene, rs1137101, are linked to developing type 2 diabetes among South Indians." (PMID 38198642, 2023). "The db/db mouse, whose leptin receptor is mutated, is a commonly used model of type 2 diabetes." (PMID 36935456, 2023). "The reason may be that the db/db mice used in this study are a spontaneous type 2 diabetic model caused by a defect in the leptin receptor gene located on chromosome 4,25 thus stimulating appetite, as shown in our data for energy intake." (PMID 37060584, 2023). "Db/db mouse was a model of spontaneous type 2 diabetes with leptin receptor-deficient." (PMID 35449001, 2022). "In a type 2 diabetes model of leptin-receptor-deficient (db/db) mice, orally administered hidrosmin (600 mg/kg/day) for 16 weeks markedly improved vascular function in aorta and mesenteric arteries without affecting vascular structural properties, as assessed by wire and pressure myography." (PMID 36552707, 2022). "In addition, the intravitreal injection of an miR-21 inhibitor ameliorated inflammation and reduced microvascular damage in the retina of leptin receptor-deficient (db/db) mice which are used as a genetic model of Type 2 diabetes." (PMID 36611916, 2022). "Db/db mice, leptin receptor deficiency, are widely used as an animal model of type 2 diabetes." (PMID 34562065, 2021).